GATA6 (GATA binding protein 6)
Diseases named in the same sentence as GATA6 in open-access papers (continued):
Sharing a sentence is not in itself a finding about the gene and the disease.
cancer (continued). "GATA6 can also regulate tumorigenesis in other endodermal tissues and has seemingly paradoxical functions in the same cancer type, which parallels the dose and temporal requirement of this TF during development." (PMID 32157212, 2020). "The roles of GATA6 in cancers are complicated by its effect in promoting or suppressing progression of different types of cancer." (PMID 33060563, 2020). "The cancer samples (or paracancerous samples) were considered GATA6-positive if more than 5% of the cancer cells (or biliary epithelial cells) showed GATA6-positive nuclear staining." (PMID 33060563, 2020). "The six GATA family members from GATA1 to GATA6 were explored in human cancers by the Oncomine online database." (PMID 30872657, 2019). "Our study identifies Eed, Gata6, and p21 as possible molecular targets to manipulate stem cell cycles in injury and cancer." (PMID 29415247, 2018). "In Chinese and Korean datasets (GSE54129 and GSE24375), the positive regulation of GATA6 by XBP1 was increased from normal to cancer, while it was decreased in American dataset (TCGA-STAD) during carcinogenesis." (PMID 29745833, 2018). "GATA6 is also reported to participate in cancer cell invasion and metastasis by regulating other proteins, such as urokinase plasminogen activator, slug and BMP4." (PMID 28270130, 2017). "Other oncogenes or cancer-associated genes such as CCNE1 (19q12; O15), CD44 (11p13; Y21), CDK6 (7q21.2; Y11), GATA4 (8p23.1-p22; O19), and GATA6 (18q11.2; O17) were also located in regions with high copy number gains." (PMID 29190909, 2017). "GATA6 losses were confirmed in a subset (9/100) of PDAC recently reported by the Australian Pancreas Cancer Initiative." (PMID 27325420, 2017). "Using siRNA-mediated silencing and an NR5A2 antagonist we demonstrate that NR5A2-mediated cancer cell survival is facilitated through augmentation of GATA6 and anti-apoptotic factor BCL-XL levels." (PMID 27586588, 2016). "Expression levels of several previously reported genes implicated in cancer development and progression were altered, such as DDIT3, GATA6, UPP1, FAT3." (PMID 26158411, 2015). "Venus is co-expressed with endogenous GATA6 throughout development to adulthood, and should provide an invaluable tool for examining the status of the Gata6 locus during development, as well as its silencing or reactivation in cancer or other disease states." (PMID 26498761, 2015). "The transcription factor GATA-6 is believed to be involved in the development of cancer by downregulating Wnt antagonist Dickopf-1 and by promoting transcription of important Wnt ligands." (PMID 26301867, 2015). "Our data from mouse ESCs stably expressing a constitutively active form of the p110 subunit of PI3K corroborates these findings and show that the PI3K-mediated increase in Gata6 expression is not limited to cancer cell populations." (PMID 25165462, 2014). "Amplification MCRs were more common in BRAFmut/MSS than BRAFwt/MSS cancers at 8q24.21 (Myc), and 18q11.2 (GATA6, CTAGE)." (PMID 24651849, 2014). "Examples included GATA6 oncogene that showed an increased promoter 5-hmC in cancer when compared with control." (PMID 23861445, 2013). "Amplification lead to increased expression in these same lesions, and parallels prior observations GATA6 protein overexpression in pancreatic intraepithelial neoplasia and cancer." (PMID 21811562, 2011). "Forced overexpression of GATA6 in cancer cell lines enhanced cell proliferation and colony formation in soft agar in vitro and growth in vivo, as well as increased Wnt signaling." (PMID 21811562, 2011). "We also noted a significant relationship among GATA6 copy number and overall survival, in that patients whose resected cancers had a copy number ≥2.3, or nuclear overexpression, had a longer overall survival than those patients without copy number gain." (PMID 21811562, 2011).
cancer (continued). "In the current study, we further analyzed the details of GATA4 and GATA6 expression in ovarian tissues and cancer, and examined the impact of the reduction of GATA6 in mice on ovarian surface epithelial transformation." (PMID 19649254, 2009). "This study examined the expression of GATA 4 and GATA6 in ovarian surface epithelial cells and carcinomas in detail, and found that the loss of GATA4 is more wide spread and often precedes GATA6 in the transformation of ovarian surface epithelia." (PMID 19649254, 2009). "GATA6 joins a growing list of cancer genes with key roles in normal human development but pathogenic roles in cancer when aberrantly expressed." (PMID 18535672, 2008). "GATA-6 expression seemed to be diminished in carcinoma cells as compared to the adjacent normal colon mucosa." (PMID 18405344, 2008). "In our preliminary analyses, we found that intense GATA-6 immunoreactivity is characteristic of the border regions of malignant tissue and the invasive parts of the carcinoma." (PMID 18405344, 2008). "The importance of GATA6 in gene expression and regulation has recently been reported in many human cancers, including lung cancer, gastric cancer, and colorectal cancer, and the downstream targets have been identified in a series of essential signaling pathways during carcinogenesis." (PMID 37692474, 2024). "The master regulatory role of GATA4 and GATA6 in organogenesis and cell specification, as well as their lineage survival nature, challenges the investigation of their broad function in gene-regulatory molecular pathways in cancer." (PMID 39456519, 2024). "Moreover, several regulons showed decreased activity in primary cancer cells, including GATA6, which is significantly reduced in UCEC, OV, PDAC and CRC." (PMID 37914932, 2023). "In addition, the study found that two genes associated with subtypes, GATA binding protein 6 (GATA6) and v-ki-ras2 kirsten rat sarcoma viral oncogene homolog (KRAS), implicated in both aspects of normal development and cancer pathophysiology." (PMID 36476236, 2022). "Evading the dependency on Wnt signaling, for example, by bypassing the intrinsic GATA6-mediated differentiation program might drive cancer progression, invasion, and metastasis." (PMID 35536676, 2022). "Targeting GATA6 combined with an anti‐PDL1 antibody might provide an effective strategy for cancer therapy." (PMID 36336787, 2022). "In addition to its effects on CCA, GATA6 has been reported to enable the self-renewal of cancer stem cells and to promote tumorigenesis and metastasis in colon cancer." (PMID 33060563, 2020). "It has been reported that GATA6 plays different roles in different cancer types." (PMID 33060563, 2020). "Based on our data and those from previous studies, GATA6 promotes cancer progression and might be a potential target for anticancer biotherapy in patients with some digestive cancers, including CCA." (PMID 33060563, 2020). "MiR-363 downregulates REG4 via suppressing GATA6 and promotes cancer cells growth." (PMID 33489872, 2020). "Moreover, we found that the cancer tissue with high expression levels of miR‐944 showed GATA6 protein expression negativity (14/16)." (PMID 30873717, 2019). "Our findings demonstrate that sebaceous fate during cancer is controlled by Lef1 and Gata6." (PMID 30886049, 2019). "Again, we identified motifs for the HNF4, GATA, FOXA, and HNF1 transcription factor subfamilies in this analysis that all exhibited greater localized accessibility in cancer, with the GATA6 and HNF1B motifs showing particularly strong increases in footprinting depth across the motif itself." (PMID 30962179, 2019). "Our findings reveal that Gata6 controls sebaceous gland development and cancer." (PMID 30886049, 2019). "GATA6 participates in cancer progression by regulating certain key molecules." (PMID 28270130, 2017).
cancer (continued). "In addition to metastasis, GATA6 is reported to play important roles in tumourigenesis, self-renewal of cancer stem cells, and proliferation and apoptosis of various types of cancer." (PMID 28270130, 2017). "Dysregulation of GATA6 has been reported in several types of cancers." (PMID 28270130, 2017). "Importantly, the inhibition of JAK/STAT signaling by the STAT3 inhibitor restored GATA6 expression as well as the expression of TFF1/2 in cancer cell lines." (PMID 27598141, 2016). "Previous researchers have reported that promoter methylation of GATA6 was observed in human cancer." (PMID 27598141, 2016). "Interestingly, adjacent normal tissues showed a significantly higher expression of GATA6 than that of cancer tissues." (PMID 27598141, 2016). "In adult mice, the Gata6H2B-Venus allele may prove useful for studies of disease states, such as cancer models, in which Gata6 activity may be aberrantly regulated." (PMID 26498761, 2015). "Furthermore, GATA-4, GATA-6 and Ihh expression is altered in premalignant dysplastic lesions and reduced in overt cancer." (PMID 18405344, 2008). "Our preliminary results suggest high expression of GATA-6 in the invasive edges of the carcinomas." (PMID 18405344, 2008). "Despite the well-established role of GATA6 in development, its function in cancer remains unclear." (PMID 40216762, 2025). "Interestingly, resident macrophages are decreased in cancer tissues compared to normal tissues in lung cancer, which could potentially explain the difference in GATA6 expression in the peritoneal macrophages between healthy donors and cancer patients." (PMID 37180125, 2023). "Therefore, the downregulation of MAF, GATA6, and DAB2 may be associated with dysregulated proteasomal function, resulting in EMT and the immune escape of cancer cells." (PMID 37779141, 2023). "miRNA targeted gene pathway interaction identified BCL7A, BCL2L1, LIN28A, KLF6, GATA6, solute carrier family genes and ZNF genes associated with erythropoiesis, cell cycle regulation, glycosphingolipid biosynthesis, cAMP, cGMP-PKG, mTOR, MAPK and PI3K-AKT signaling pathways and cancer pathways." (PMID 36295630, 2022). "Focal amplifications in BRAFmut/MSS cancers were also more common compared to BRAFwt/MSS cancers at 8q (11/33, 33% Vs 1/18, 6%; p = 0.04) predominantly at 8q24.21 covering the Myc locus, and 18q (7/33, 21% Vs 0/18; p = 0.04) affecting 18q11.2 (containing GATA6 and CTAGE)." (PMID 24651849, 2014). "Some GATA-6 expression could also be seen in the cancer lines MCF-7 and HeLa." (PMID 22174832, 2011). "To further explore the impact of GATA6 and TET1 on CAF function, we conducted scratch and transwell assays to evaluate their effect on cancer cell migration and invasion." (PMID 40216762, 2025). "Further, GATA6 was found to be directly targeted by miR-181-5p, and overexpression of this miRNA reversed the inhibitory effects of MEG3 upregulation on cancer cell proliferation." (PMID 41514651, 2025). "Canonical markers cytokeratin 17 (CK17) for the BL subtype, GATA6 for the CLA subtype, and CK19 as a pan-cancer cell marker are also useful biomarkers." (PMID 40230862, 2025). "Some epigenetic drivers appeared in multiple cancers (for example, regulatory regions of ABCC1 and VEGFA; GATA6 and FOX-family motifs), whereas others were cancer specific (for example, regulatory regions of FGF19, ASAP2 and EN1, and the PBX3 motif)." (PMID 37914932, 2023). "Consistent with observations from human snATAC-seq data analysis, we found fewer GATA6+ and GATA6high PDAC cancer cells in all liver metastases compared with in their matched primary pancreatic tumours (paired t-test, P = 0.066 and P = 0.057, respectively)." (PMID 37914932, 2023). "We used the canonical markers cytokeratin 17 (CK17) for the basal subtype, GATA6 for the classical subtype, and cytokeratin 19 (CK19) as a pan-cancer cell marker." (PMID 36781852, 2023).
cancer (continued). "We found that CD44, CDK6, GATA4, GATA6, KLF5, and KRAS, which were amplified in TCGA STAD cohort, were amplified in cancer cell clusters." (PMID 35087207, 2022). "As expected, we found genes dictating the CSC phenotype and behavior, including, but not limited to, cancer stemness (Myc and Sox) and epithelial-to-mesenchymal transition (EMT) (Gata6 and Tfcp2)." (PMID 36002648, 2022). "Current reports have documented that miR-203 is a stemness-inhibiting miRNA owing to its modulation of stemness properties through regulating the expressions of various targets in different types of cancers, including SOCS3, survivin, Bmi-1, and GATA6." (PMID 34539782, 2021). "Also, down-regulated GSK3 could induce upregulation of GATA6 in cancer cells." (PMID 34772451, 2021). "Our published and recent unpublished data indicate that GATA6 functions as an oncoprotein in CCA, contributing to cancer cell metastasis, angiogenesis and immune escape." (PMID 33060563, 2020). "To explore the role of GATA6 in the EMT of CCA cells, we first observed the expression of GATA6 and EMT markers in 91 cancer samples and 31 matched paracancerous samples by IHC." (PMID 33060563, 2020). "Differential hydroxymethylation is found in thousands of genes, most significantly in genes related to pancreas development or function (GATA4, GATA6, PROX1, ONECUT1, MEIS2), and cancer pathogenesis (YAP1, TEAD1, PROX1, IGF1)." (PMID 33077732, 2020). "Many of the validated genes bound by ZNF322A such as HMGN5, GATA6, CCAR1 and ELK4, were found to be involved in tumorigenesis in other cancers, further supporting the oncogenic role of ZNF322A." (PMID 30258097, 2019). "An identical trend was observed in a different data set, with highest expression in cancer being observed for genes activated by both HNF4A and GATA6." (PMID 30962179, 2019). "We identified 156 focal amplifications and 69 focal deletions, in well-known oncogenes, such as ERBB2, CCNE1, KRAS, MYC, EGFR, and CDK6, and cancer-related genes such as GATA4, GATA6, CD44 and ZNF217." (PMID 31570735, 2019). "Among the top 10 DRGs identified for Korean (GSE24375), six genes are GC related (ESRRG, LIMS1, GATA3, GATA6, SOX9, POU2F1) and the other four are cancer related (IRF2, RGS3, MRPL36, FOSB)." (PMID 29745833, 2018). "A recent study has also found that promoter-specific hypomethylation induces the ectopic expression of the cancer-related genes PLS3, GATA6 and TWIST1 in SS." (PMID 30701021, 2018). "Reduction of GATA6 and Dab2 expression in HIO and cancer lines is more apparent by real-time RT-PCR." (PMID 19649254, 2009). "Hydroxymethylation in genes such as GATA4, GATA6, PROX1, ONECUT1, and MEIS2, which plays an important role in development and functioning of pancreas, as well as in genes YAP1, TEAD1, PROX1, IGF1, were found involved in cancer pathogenesis." (PMID 40230862, 2025). "Furthermore, GATA6 regulon activity decreases in PDAC, CRC, OV and UCEC primary cancer cells compared with their respective CNCs." (PMID 37914932, 2023). "Dysregulation of GATA6 has been connected to cell migration in non-smooth muscle cells including cancer cells." (PMID 36523548, 2022). "To date, the millions of Gata6+ cavity macrophages found in the peritoneum, the pleura and the pericardium seem not to have drawn the attention of the cancer field for their ability to infiltrate tumors." (PMID 35906202, 2022). "Fifty-one cancer samples (56.0%) showed GATA6-positive expression, whereas all 31 paracancerous samples were negative for GATA6." (PMID 33060563, 2020). "Interestingly, all GATA family members besides GATA3 were mostly downregulated in most kinds of cancers, with upregulated vs downregulated study numbers (GATA1 1:7; GATA2 6:39; GATA3 31:36; GATA4 5:18; GATA5 1:17; GATA6 16:37)." (PMID 30872657, 2019).
cancer (continued). "This evidence, together with others showing the inverse correlation of GATA4 with GATA6 in many cancers, drives us to assume that GATA4 is no longer the protagonist as it behaved in hepatic development due to frequent loss of expression in adult liver tumors." (PMID 24498120, 2014). "Transient transfection of GATA6, but not mutant GATA6, into cancer cell lines led to decreased DKK1 mRNA expression and secretion of DKK1 protein into culture media." (PMID 21811562, 2011). "With further development of antibodies and refinement of staining procedure, we carried out immunohistochemical analysis for the expression of GATA4 and GATA6 in a panel of ovarian non-neoplastic and cancer tissues in tissue microarray." (PMID 19649254, 2009). "In the first example, GATA4 is already absent in the benign monolayer; GATA6 is positive in the monolayer cells but is lost in the adjacent cancer cells." (PMID 19649254, 2009). "The GATA family (GATA Binding Protein), which includes GATA2, GATA3, and GATA6, governs critical cellular processes such as cell migration, epithelial-to-mesenchymal transition (EMT), and metastasis, all of which play important roles in cancer formation and progression." (PMID 41155227, 2025). "For example, GATA6 expression marks the classical type and is suppressed in the basal type, and a TP63 isoform called deltaN-P63 is suppressed in the classical PDAC transcriptional program and could mark a subset of basal-like cancer cells." (PMID 37124496, 2023). "The negative regulation of REG4 by GATA6 was reversed to be positive from normal to cancer, the positive regulation of CA9 by GATA6 in normal tissue disappeared in cancer and the negative regulation of STC1 by GATA6 in normal stage was also disappeared in cancer." (PMID 35421923, 2022). "In contrast, histone H3 and H4 acetylation of the GATA6 locus in many cancer cells was not reduced and traces of GATA6 mRNA could be detected by RT-PCR, indicating that GATA6 gene is not transcriptionally silenced but the message is suppressed by other mechanism(s)." (PMID 19649254, 2009). "Examples of tissue-specific regulons include FOXA1 and GATA3 in BRCA non-basal cancer, KLF4 and FOSL1 in CESC and HNSCC, HNF1A and KLF9 in ccRCC, and HNF4G and GATA6 in CRC and PDAC." (PMID 37914932, 2023).